IL1B (interleukin 1 beta)
Diseases named in the same sentence as IL1B in open-access papers (continued):
Sharing a sentence is not in itself a finding about the gene and the disease.
infection (continued). "To further evaluate whether Caspase-1/11 and Gsdmd were involved in the IL-1β release in response to the SS2 infection in vivo, we also injected IP WT, Caspase-1/11−/−, and Gsdmd−/− mice with lower dose of 2 × 108 CFU SS2." (PMID 32922370, 2020). "However, we noted small amounts of IL-1β secretion from VX-765 treated cells exposed to H. pylori/Nigericin, which is equivalent to the IL-1β production solely by infection." (PMID 32230726, 2020). "Furthermore, oxidative stress following infection can induce the transcription factor NF-kB, which subsequently leads to increased levels of inflammatory cytokines, including interleukin (IL)-1β, IL-6, IFN, and TNF." (PMID 32161622, 2020). "Liver IL-1β expression in dual-transgenic tilapia was 3.8-fold lower and 1.4-fold lower than in wild-type tilapia at 3 h and 6 h post-infection, respectively; muscle IL-1β expression in dual-transgenic tilapia was 2.8-fold lower than in wild-type tilapia at 3 h after injection." (PMID 32730353, 2020). "Although IL-1β is a conventional pro-inflammatory cytokine, our study unveils an unexpected and surprising role of this cytokine in inducing functionally robust Foxp3+ cells, namely Treg17 cells, during the early phases of infection." (PMID 33240286, 2020). "However, in the present study, we showed that after infection with Mtb, AMTBs upregulated the IL1B gene." (PMID 32373118, 2020). "Therefore, a potential correlation between testosterone and IL-1β serum level in female mice after infection has been analyzed." (PMID 32431696, 2020). "Endogenous production of G-CSF is largely triggered by infection and tissue damage in response to production of several pro-inflammatory stimuli such as the cytokines interleukin-1 beta (IL-1β) and tumor necrosis factor-alpha (TNFα), as well as bacterial lipopolysaccharides (LPS)." (PMID 33233675, 2020). "Upon infection, IL-1β gene expression increased 356-fold, 93-fold, 17-fold, and 14-fold in the liver, testis, spleen and kidney, respectively, while iNOS gene expression increased 294-fold, 29-fold, 18-fold, and tenfold in the liver, spleen, kidney, and testis, respectively." (PMID 33239112, 2020). "Finally, infection of BMDMs with isolate 6C4 in the presence of an inflammasome activator (as ATP), an upregulation of IL-1β was observed." (PMID 32327653, 2020). "Consequently, the capacity of these cells to produce IL-1β following infection with the SLY-negative strain 89-1591 was evaluated using bone marrow-derived dendritic cells (bmDCs), which are a well-characterized model of conventional DCs." (PMID 32098284, 2020). "Finally, we measured plasma levels of TNF-α, IFN-γ, IL-6, and IL-1β cytokines by an ELISA to determine if systemic secretion of cytokines offers an indication of anti-parasite protective immunity after infection and re-infection." (PMID 33414785, 2020). "Mouse infection experiments with C. albicans mutants lacking ECE1, or the candidalysin-encoding sequence only, showed that the candidalysin-dependent induction of IL-1β release transfers from the macrophage in vitro infection model to in vivo models of systemic candidiasis." (PMID 32722029, 2020). "Furthermore, Il22−/− mice succumbed earlier to infection, which was associated with increased local production of TNF-α and IL-1β, reduced IL-1ra, as well as increased lung inflammation." (PMID 32517114, 2020). "Other factors with significantly higher levels in WNV-infected cells than in USUV-infected NSCs were the apoptosis factor caspase-3, and the pro-inflammatory cytokine IL-1β, which play an important role in neural damage by flaviviruses and infection control by the host." (PMID 32806715, 2020). "Interestingly, as judged by the decrease in transcript abundance, DC infection with Ab-opsonized amastigotes interfered with various immune-related processes, including NF-κB signaling and the production of IL-1β, IL-12, and eicosanoids." (PMID 32582184, 2020).
infection (continued). "For instance, a higher expression of IL-1β and IL-18 may indicate that the infection is due to a gram + bacteria while IL-6 and TNF would have a higher expression in gram negative infections." (PMID 32655547, 2020). "IL-1β activated autophagy to control pathogens infection, such as M. tuberculosis." (PMID 33013900, 2020). "Indeed, most of the infections can trigger the release of IL-1β from the inflammasome followed by the production of IL-6 that increases the circulating levels of C-reactive protein, the prototypical acute-phase reactant." (PMID 32719685, 2020). "Since IL-1β expression was significantly reduced in the brain of TLR2 KO mice as well as TLR2-deficient microglia and macrophages, we next examined the functional importance of caspase-1 during S. aureus craniotomy infection using caspase-1 KO mice." (PMID 32290861, 2020). "Interestingly, Il1b / Il6 / Irg1 expression increased at 24 hpi after infection in BALB/c macrophages infected with all the strains, except for VFRA." (PMID 32925918, 2020). "However, infection of three different wild-type strains and 11 well-known isogenic mutants did not reveal any critical effect on inflammasome function and mature IL-1β secretion." (PMID 32230726, 2020). "IL-1β has been implicated in some infection models, but IL-1α activity in brain infection has not previously been reported." (PMID 32703941, 2020). "We presume that ORF2 of EHV-1 also may have a similar function, thereby Ab4-wt infection in PBMC results in decreased release of IL-1β, while ORF2 deletion restores expression." (PMID 32911663, 2020). "IL-1β mediates the host inflammatory response to prevent infection." (PMID 32565729, 2020). "The age of the animals at the time of blood collection had a limited effect, showing the more intense IL-1β response of monocytes from younger and older cats, and higher IL-10 mRNA levels in the monocytes of younger cats during the first six hours after infection." (PMID 33121170, 2020). "During infection, the concentration of IL-1β decreased significantly for PBS and LPPIII groups." (PMID 33237133, 2020). "Additionally, infection with the T3SS-3 mutant drastically reduced IL-1β release from infected cells compared to the wild type." (PMID 33137811, 2020). "However, NLRP3-independent routes to IL-1β release have been reported in mouse infection models, leaving the role for NLRP3 in vivo less clear." (PMID 32385301, 2020). "Indeed, IL-1β, IL-18, and IL-33 also contribute to the host defence against infections by regulating Th17, Th1, and Th2 CD4 T cell responses." (PMID 32754155, 2020). "Next, we sought to determine whether IL-1β production by BMDMs exposed to N. caninum required actual infection mechanisms by the parasite or if different antigenic fractions were capable of inducing the release of the cytokine." (PMID 32523898, 2020). "Interestingly, patients with prolonged viral RNA shedding demonstrated lower levels of IL‐1β and IL‐17A during the acute phase of infection." (PMID 32742654, 2020). "Levels of interleukine (IL) 1α and IL1β went up immediately after infection in PBS NC99 mice." (PMID 32582220, 2020). "Specifically, SAMP8 mice showed a general increase of Il1b expression in the cerebral cortex and, most noticeably, an extreme activation of the gene expression of Il1b, Il6 and Tnf induced by LPS in the hippocampus at young age followed by null responsiveness to infection-like stimulus at old age." (PMID 33584248, 2020). "Additionally, to form the inflammatory microenvironment, the immune response is initiated to activate the releasing of pro-inflammatory cytokines such as IL-1β and IL-6 when damage and infection occur." (PMID 33375269, 2020). "Interestingly, HIV+ and HIV+Meth samples displayed increased extracellular IL-1β levels on day 1 post infection, while IL-1β mRNA levels were significantly increased at day 2 post infection." (PMID 32117283, 2020).
infection (continued). "Infection with Mtb in the post-drug relapse phase, however, was associated with pulmonary activation of several pro-inflammatory cytokines and chemokines that have established roles in enhancing HIV replication including IL-1β, IL-6, TNF-α, and CCL-2." (PMID 32373548, 2020). "Interestingly, it was shown before that aged male mice treated with testosterone had reduced pulmonary IL-1β levels compared to aged male mice with low testosterone levels after infection." (PMID 32431696, 2020). "Elevated IL-1β production might be related to infection- or inflammation-induced spontaneous term parturition and preterm birth." (PMID 32188057, 2020). "Indeed, H37Rv and isolate 411 released 52% and 37% less IL-1β upon infection of Nlrp3−/− cells as compared to wildtype iBMDMs." (PMID 32111888, 2020). "The pro-inflammatory interleukin 1-beta was identified only in vacuolization, interleukin receptors were found in both infection stages, and two interleukin enhancer-binding factors were increased in the propagation stage when compared to the vacuolization proteome." (PMID 33255149, 2020). "Therefore, the production of the inflammatory cytokine IL-1β increases in tissue damage, environmental stress, infection, or chronic inflammation." (PMID 31952466, 2020). "Furthermore, the expression of TNF, IL-6, and IL-1β mRNA and protein levels were significantly increased in Ppara-/- BMDMs, compared with Ppara+/+ BMDMs, after Mabc infection (protein and mRNA, respectively)." (PMID 32155958, 2020). "Macrophages showed the highest amounts of IL-1β after infection with any bacteria at 24 h." (PMID 31947665, 2020). "To further support our hypothesis that VPRH induces a rapid, inflammasome-mediated cell death in BMDMs, we sought to determine whether the inflammasome-dependent cytokine, IL-1β, was secreted upon infection with V. proteolyticus." (PMID 32013758, 2020). "However, infection-induced small amounts of IL-1β secretion gradually increased at a later time point, which again suggests an inflammasome/caspase-1 independent mechanism for this in human THP-1 cells." (PMID 32230726, 2020). "Moreover, gene expression of IL-1β was also decreased in 26695ΔFlaA-treated cells at 2 h after infection." (PMID 32582201, 2020). "The correlation with markers of infection and inflammation has been confirmed by others, with lower plasma glutamine levels found to be associated with lower albumin levels, higher CRP levels, and higher circulating IL-1β and IL-6 levels." (PMID 32028696, 2020). "In addition, IL-1β is a proinflammatory cytokine involved in the recruitment of immune cells to the site of infection." (PMID 32397672, 2020). "There is a notable buildup in the concentration of IL-1β as the infection progressed." (PMID 32523898, 2020). "Furthermore, excess IL-1β production and cell death in C. koseri-infected Gate-16−/−Gabarap−/− macrophages were observed in manners dependent on bacterial dose and infection time." (PMID 33042141, 2020). "The biofilm or any aggregate formed between C. albicans and P. gingivalis cells, while interacting with THP-1 triggered a significant increase in Il-1β production compared to mono-species infection, suggesting the cooperation of both microbes towards the host cells." (PMID 32183255, 2020). "IL-1β controls the recruitment of neutrophils to the infection site to destroy the damaged tissue." (PMID 32182890, 2020). "The pathophysiological function of IL-1β during the process of infection-related inflammation in the brain remains unclear." (PMID 32070376, 2020). "The immune response mounted to an ongoing infection may be divided into two components: the proinflammatory cytokines such as TNFα and IL1β; and anti-inflammatory cytokines such as IL11." (PMID 33182721, 2020).
infection (continued). "On the other hand, endothelial cells infection and activation of macrophages in the pulmonary alveoli are the main source of pro-inflammatory cytokines such as IL-1b, IL-6, IFN-γ, IL-8, and TNF-α triggering the acute inflammatory response, known as “cytokine storm”." (PMID 33117379, 2020). "Also, the infection witnessed an upsurge in pro-inflammatory cytokines and chemokines (IL-6, IL-1β, TNF-α, IFN-γ, and IL-8)." (PMID 33262955, 2020). "However, IL-1β production in liver and spleen was elevated, with the highest levels at 6 h and 12 h post-infection (p.i.)." (PMID 32098284, 2020). "Furthermore, mRNA levels of factors activated by the NLRP3 inflammasome (IL-1β and IL-18) were significantly decreased in Gm28309 overexpressed cells, but higher in S2308 infection group, as well as protein secretion levels detected using ELISA." (PMID 33414782, 2020). "There was low level expression of IL1β throughout the infection and there was a surge at 20 dpi." (PMID 32076422, 2020). "Our results showed IL1-β in the top upstream regulator genes controlling infection response." (PMID 32178732, 2020). "Inflammasome-mediated secretion of IL-1β and IL-18 is aimed at eliminating the infectious pathogen through the induction of secondary mediators and the recruitment of additional immune cells to the infection site and/or pyroptosis of the infected cells." (PMID 32801995, 2020). "Moreover, our data are in line with and extend the reports showing that naringenin decreases IL-1β expression in irradiation-induced injury and fibrosis post-infection with Mycoplasma pneumoniae." (PMID 33182380, 2020). "Another proinflammatory cytokine produced in response to an ongoing infection is IL1β." (PMID 33182721, 2020). "Our results reveal a previously unknown role of the IL-1β/MyD88/mTOR axis in modulating mucosal Tregs during an infection." (PMID 33240286, 2020). "However, using in vivo studies, caspase-1-independent IL-1β processing is the prevailing source of mature IL-1β during the acute phase of infection, which is characterized by strong neutrophil infiltration." (PMID 32722029, 2020). "To further evaluate whether SLY was involved in the IL-1β release in response to the SS2 infection in vivo, we injected IP WT mice with a lower dose of 2 × 108 CFU SS2 or ∆SLY." (PMID 32922370, 2020). "And then the downstream pathway is activated, thereby promoting the expression of NF-κB and the secretion of inflammatory cytokines, such as IL-1β and IL-18, which play a key role in recruiting neutrophils to sites of infection and promote inflammatory anti-bacterial immune responses." (PMID 32823867, 2020). "Interleukin-1 beta has been indicated as one of the hallmarks of Atlantic salmon response to AGD with its transcript showing a linear pattern of up-regulation throughout the disease progression starting from as early as day 12 post infection." (PMID 30873203, 2019). "Interestingly, the production of IL-1β in T. gondii-infected cells treated with SF was significantly increased and the expression of IL-10 was gradually decreased compared with the infection group." (PMID 31075881, 2019). "Indeed, caspase-1, activated in response to infection by a macromolecular protein complex termed ‘inflammasome’, is able to cleave pro-IL-1β into its mature form, contributing to host inflammatory response and tissue damage." (PMID 31026281, 2019). "Only infection with L2 stimulated production of GM-CSF, IL-1β, IL-6, IL-32, and CXCL12." (PMID 32039039, 2019). "The authors concluded that the microbe-mediated IL-1β production serves as an autocrine signal that amplifies neutrophil infiltration at the infection sites and may also aid in parasite dissemination to the spleen." (PMID 31847221, 2019). "Moreover, this reduction rate was by more than 70% at 24 hpi or later, suggesting a decisive role of nsp2 in modulating the production of TNF-α and IL-1β during infection." (PMID 31561412, 2019).
infection (continued). "Indeed, treatment of WT macrophages with MCC950 decreased inflammasome-dependent IL-1β secretion upon El Tor infection." (PMID 31736941, 2019). "Histologic evaluation of skin samples neighboring IL-1β-loaded pumps at the peak of infection revealed extracellular MPO lining of the contact regions as well as intra- and extracellular citrullinated histones in the tissues surrounding the contact regions with the pumps." (PMID 31156635, 2019). "Similarly, subsequent production of IL-1β, induced by macrophages, also reached the highest levels after 3, 5, and 7 days of HAdV-3 and HAdV-7 infection." (PMID 30626350, 2019). "Interestingly, IL-1β which we noted only in HFK-2 cells at 24 h post infection can suppress IL-6 dependent signaling Notably, we observed a 30.3- or 7.1-fold increase in IL-8 production for HFK-2 cells infected with L2 or D, respectively." (PMID 32039039, 2019). "In the present study, IL-6 and IL-1B were proven to be induced throughout the infection process by qRT-PCR, which reinforced the hypothesis." (PMID 31130962, 2019). "Moreover, IL-1β secretion upon nga(G330D) or wt infection is differentially affected by PEGs, whereas the pattern of cell death inhibition seems independent of infecting strain." (PMID 31275321, 2019). "Moreover, apoptosis induction, tight junction redistribution, and an increased inflammatory response—represented by TNF-α, IL-1β, and IL-6 secretion—was observed in co-cultures after infection and reversed by curcumin." (PMID 31569415, 2019). "Moreover, this involvement occurs at an early stage of infection process because IL-1β levels were only decreased upon NLRP3 inhibitor treatment on day 1 post-infection." (PMID 30964929, 2019). "IL-1β production was dependent on inflammasome activation since Casp1/11 deficient macrophages failed to trigger IL-1β production in response to the infection." (PMID 31211814, 2019). "In addition, in the livers, IFN-α1, IFN-β, TNF, and IL-1β mRNA and, in the testes, IFN-α1, IFN-β, TNF, IL-1β, and IL-6 mRNA levels increased following infection of Ifnar1−/− mice." (PMID 31511023, 2019). "Thus, we added the proteasome inhibitor MG-132 or the broad autophagy inhibitor 3-MA to our infections and measured the effect on IL-1β release." (PMID 31275321, 2019). "Although the activation of NLRP3 inflammasome is largely beneficial to the host defense during infections and metabolic processes, over production of IL-1β and IL-18 results in sterile inflammation, which can increase the risk of developing metabolic and autoinflammatory diseases among patients." (PMID 30873162, 2019). "However, by day 3 of infection, a significant increase in IL-1β transcripts was observed for all three concentrations of PACAP." (PMID 31105711, 2019). "Although this cytokine may play a role in the initiation of the early immune response and has multiple effects on gene expression during inflammation, IL-1β expression was likely suppressed in rainbow trout at later stages of the infection." (PMID 31220151, 2019). "Thus, to properly control infection and prevent detrimental tissue damage, it seems crucial that IL-1β is maintained at appropriate levels." (PMID 31275321, 2019). "Many of these proinflammatory mediators, including IL-6, MCP-1, TNFα, IFNγ, RANTES and IL-1β, were also present at high concentrations on days 4 and 6 of infection in the spleen, a major target tissue for SFTSV replication and pathology, as well as other tissues." (PMID 31546590, 2019). "Interestingly, they also observed an increased release of IL-1α and IL-1β pro-inflammatory cytokines from cells at the infection sites in neutrophil-depleted mice, one week post-infection." (PMID 31847221, 2019). "Similarly, active caspase-1, mature IL-1β, and secondsreted IL-1β were induced by infection with either E. coli or P. mirabilis, and this induction was reduced by NLRP3 knockdown." (PMID 30823406, 2019). "Kp52145 infection also upregulated the levels of tnf-α and il-1β." (PMID 31796543, 2019).